HNF4G (hepatocyte nuclear factor 4 gamma)
Description:
Transcription factor. Has a lower transcription activation potential than HNF4-alpha.
Synonyms: NR2A2; NR2A3
Tractability: Small molecule: it belongs to a druggable protein family.
Target class: Nuclear hormone receptor subfamily 2 group A; Nuclear hormone receptor subfamily 2; Nuclear receptor; Transcription factor; Nuclear hormone receptor subfamily 2 group A member 2
Gene: Protein-coding gene on chromosome 8 (75,407,914 to 75,566,834, forward strand). Ensembl gene ENSG00000164749.
Subcellular location: Nucleus
Subcellular location (Human Protein Atlas): Nucleoplasm; Cytokinetic bridge; Cytosol; Mitotic spindle
Pathways (Reactome):
Developmental Biology: Regulation of gene expression in beta cells
Gene expression (Transcription): Nuclear Receptor transcription pathway
Gene Ontology:
Molecular function: DNA-binding transcription activator activity, RNA polymerase II-specific; RNA polymerase II cis-regulatory region sequence-specific DNA binding; DNA-binding transcription factor activity; DNA-binding transcription factor activity, RNA polymerase II-specific; nuclear receptor activity; sequence-specific DNA binding; zinc ion binding
Biological process: positive regulation of transcription by RNA polymerase II; cell differentiation; regulation of transcription by RNA polymerase II; intracellular receptor signaling pathway; positive regulation of DNA-templated transcription; regulation of DNA-templated transcription
Cellular component: cytosol; nucleoplasm; chromatin; nucleus
Genetic constraint (gnomAD): Loss-of-function variants: 6 observed, 28.13 expected, observed/expected ratio (o/e) 0.21, 90% interval 0.12 to 0.42. The upper end of that interval is the gene's LOEUF score, 0.42, which puts it in group 1 of 6, group 1 being the genes least tolerant of losing a copy. Missense variants: 306 observed, 354.32 expected, observed/expected ratio (o/e) 0.86, 90% interval 0.79 to 0.95. Synonymous variants: 118 observed, 119.94 expected, observed/expected ratio (o/e) 0.98, 90% interval 0.85 to 1.15.
Homologues: Orthologues: chimpanzee HNF4G (99% identical), macaque HNF4G (99% identical), rabbit HNF4G (98% identical), dog HNF4G (97% identical), guinea pig HNF4G (96% identical), pig HNF4G (96% identical), mouse Hnf4g (95% identical), rat Hnf4g (94% identical), tropical clawed frog hnf4g (82% identical), zebrafish hnf4g (67% identical), Caenorhabditis elegans nhr-69 (31% identical), Drosophila melanogaster usp (27% identical), and 25 more. Paralogues in human: HNF4A (68% identical), RXRA (36% identical), RXRB (34% identical), RXRG (33% identical), NR2F1 (30% identical), NR2F2 (30% identical), NR2F6 (30% identical), NR2C2 (27% identical), NR2E3 (26% identical), NR2C1 (26% identical), NR2E1 (26% identical).
Diseases named in the same sentence as HNF4G in open-access papers:
HNF4G is named in the same sentence as 34 diseases in open-access papers, as found by Europe PMC text mining. Sharing a sentence is not in itself a finding about the gene and the disease. The quoted sentences say what the papers report.
pancreatic cancer (9 papers, 2018 to 2024). "In pancreatic cancer, HNF4G was also found to be induced by SMAD4 deficiency, promoting progression and metastasis but being suppressed by the metformin/APMK signaling pathway." (PMID 36923501, 2023). "A research showing GWAS pathways associated with pancreatic cancer susceptibility factors proposed a link between HNF4G inherited variation for pancreatic development." (PMID 33879152, 2021). "Our results in the present study are consistent with these findings and extend the oncogenic role of HNF4G to pancreatic cancer." (PMID 32737864, 2021). "In addition, it can also inhibit the progression of SMAD4-deficient pancreatic cancer by enhancing AMPK-mediated phosphorylation and ubiquitination degradation of HNF4G protein, providing the possibility of targeted therapy for pancreatic cancer." (PMID 38012210, 2023). "However, the function and action mechanism of HNF4G in pancreatic cancer remain unknown." (PMID 32737864, 2021).
prostate carcinoma (9 papers, 2018 to 2025). A carcinoma that arises from epithelial cells of the prostate gland. "Experimentally, exogenous expression of HNF4G in prostate cancer cells leads to expression of the GI transcriptome and resistance to AR pathway inhibition." (PMID 40553565, 2025). "A recent study however revealed an intriguing role for HNF4G in castration-resistant prostate cancer." (PMID 32998360, 2020). "In addition, aberrant activation of a gastrointestinal differentiation program in prostate cancer, which can mediate castration resistance, is driven by HNF4γ in cooperation with FoxA1." (PMID 30475207, 2018). "Previous studies have suggested that HNF4G may act in promoting cell proliferation and invasion in several types of human cancer, such as bladder cancer, lung cancer and prostate cancer." (PMID 32737864, 2021). "We have uncovered that aberrant upregulation of GI master regulators HNF4G and HNF1A alters enhancer landscape and chromatin accessibility conducive to the expression of GI-specific transcriptome in prostate cancer cells." (PMID 40553565, 2025). "Indeed, HNF4G was found to act as a pioneer factor for the aberrant gastrointestinal lineage transcriptional program found in one-third of these patients, while ectopic HNF4G expression in a prostate cancer cell line reduced its sensitivity to hormone deprivation." (PMID 32998360, 2020). "In the colon cfDNA pool, TFs EVX2, DLX2, HNF1A, HNF4A, and HNF4G and TFs AR and HOXB13 in the prostate cancer cfDNA pool had increased accessibilities, whereas FOXA1 exceeded the >5 z-score threshold in both the prostate and breast pool." (PMID 31604930, 2019). "We hypothesized that FOXA1 was the PF for HNF4G (and possibly HNF4A), as seen with other NRs in breast and prostate cancer that require FOXA1." (PMID 41168397, 2025). "Researchers found that HNF4G/HNF1A was highly expressed in prostate cancer, and that the lack of HNF4G/HNF1A inhibited the growth of prostate cancer cells." (PMID 34234870, 2021). "Interestingly, a recent study SPINK1-positive castrate resistant prostate cancer identified POU5F1/OCT4 as part of a gastrointestinal gene signature present in SPINK1-positive prostate cancer and regulated by HNF1A and its target gene HNF4G." (PMID 30074477, 2018).
bladder cancer (7 papers, 2015 to 2022). "A member of orphan nuclear receptor family, HNF4G has been mainly implicated in lung and bladder cancer where it is believed to promote cell proliferation." (PMID 36235682, 2022). "miR-34a can downregulate the protein levels of HNF4γ and Notch1 in bladder cancer and endometrial cancer cells." (PMID 33221743, 2020). "The hepatocyte nuclear factor 4 gamma (HNF4G), a member of orphan nuclear receptors, is up-regulated and functions as an oncoprotein in bladder cancer." (PMID 29719587, 2018). "miR-34a-HNF4G axis is an important pathway modulating cell viability, proliferation, and invasion of bladder cancer cells." (PMID 25878394, 2015). "In this study, we explored the regulative network of miR-34a in bladder cancer and firstly reported that HNF4G is a direct downstream target of miR-34a." (PMID 25878394, 2015). "One recent study observed that orphan NR HNF4G was remarkably upregulated in bladder cancer and this upregulation gives rise to bladder cancer progression through promoting cancer cell growth and invasion." (PMID 25878394, 2015). "Hepatocyte nuclear factor 4-gamma (HNF4G) belongs to the orphan nuclear receptor superfamily and has been shown to influence growth and invasiveness in bladder cancer; its place in our high-risk score group suggests its function on NSCLC which deserves further exploration." (PMID 36193311, 2022). "However, considering the significant effect of miR-34a-HNF4G axis in modulating cell viability, proliferation, and invasion of bladder cancer cells, this axis at least is one of the most important regulative paths." (PMID 25878394, 2015). "Therefore, miR-34a-HNF4G axis is an important pathway modulating cell viability, proliferation, and invasion of bladder cancer cells." (PMID 25878394, 2015). "In fact, the regulative network of miRNAs is quite complex, we could not exclude the possibility that other miRNAs are involved in the regulation of HNF4G in bladder cancer or miR-34a could modulate bladder cancer through other pathways." (PMID 25878394, 2015). "In bladder cancer, one recent study found that HNF4G is a most frequently upregulated gene and its overexpression could promote bladder cancer growth and invasion through regulating the hyaluronan synthase 2 gene." (PMID 25878394, 2015). "HNF4G activated the transcription of HAS2 by interacting with the promoter/enhancer region of HAS2 to promote the growth and invasion of bladder cancer cells." (PMID 34819492, 2021).
lung carcinoma (7 papers, 2018 to 2023). "Considering the results of GSEA that HNF4G expression in lung cancer patients was closely associated with cell cycle and apoptosis pathways, we then evaluated the effects of HNF4G knockdown on cell cycle and apoptosis of H358 and H292 cells." (PMID 29719587, 2018). "We found that the expression of HNF4G in lung cancer tissues was closely associated with tumor size (P < 0.05)." (PMID 29719587, 2018). "This suggests that Hnf4g is playing a role in gene regulation even in transformed cancer cells, which is in line with recent reports on other cancer types, which revealed that dysregulated Hnf4g is associated with pancreatic, prostate, and lung cancer." (PMID 29945941, 2018). "Hsa-miR-320b also inhibits lung cancer angiogenesis and tumor growth by inhibiting the hepatocyte nuclear factor 4 gamma (HNF4G) and insulin-like growth factor 2 mRNA-binding protein 2 (IGF2BP2) expression." (PMID 35958401, 2022). "It has been reported that HNF4G can exert a carcinogenic effect by promoting cell proliferation and inhibiting cell apoptosis in lung cancer." (PMID 35620002, 2022). "Compared with the adjacent normal lung tissue, the expression of HNF4G is significantly up-regulated in lung cancer tissues." (PMID 35013450, 2022). "HNF4G mRNA and protein expression was frequently up-regulated in lung cancer tissues compared to normal lung tissues." (PMID 29719587, 2018). "Transfection with a small interference RNA (siRNA) targeting HNF4G in two lung cancer cell lines (H358 and H292 cells) significantly inhibited cell proliferation via arresting cells at G1 phase and inducing cell apoptosis." (PMID 29719587, 2018). "To identify pathways correlated with HNF4G, we performed Gene set enrichment analysis (GSEA) comparing lung cancer samples with high expression and low expression of HNF4G using TCGA dataset." (PMID 29719587, 2018). "In this study, we investigated the expression and biological functions of a nuclear receptor, HNF4G in lung cancer." (PMID 29719587, 2018). "In the present study, we observed that HNF4G expression was elevated in lung cancer tissues as compared to adjacent normal lung tissues." (PMID 29719587, 2018). "Collectively, our data indicate that HNF4G exerts as an oncogenic role in lung cancer by promoting cell proliferation and that HNF4G expression is a potential prognosis factor for lung cancer." (PMID 29719587, 2018). "HNF4G functions actively in the promotion of cell proliferation and cell cycle progression, the inhibition of cell apoptosis in lung cancer, and AKT signal pathway is possible to be involved in the biological function of HNF4G." (PMID 29719587, 2018). "Although further study with large sample size is needed to clarify the relation, our study suggests the potential clinical value of HNF4G in lung cancer." (PMID 29719587, 2018). "Functional assays showed that RNA interference-mediated inhibition of HNF4G significantly repressed lung cancer cell proliferation in vitro and in vivo." (PMID 29719587, 2018). "In the current study, we found that HNF4G expression was remarkably up-regulated in lung cancer tissues as compared with adjacent normal lung tissues." (PMID 29719587, 2018). "Our data indicate that HNF4G exerts proliferation-promoting effect on lung cancer cells via speeding up cell cycle transition and inhibiting cell apoptosis." (PMID 29719587, 2018). "Our results suggests that AKT pathway is a potential upstream regulator of HNF4G in lung cancer." (PMID 29719587, 2018). "Next, we investigated the biological functions of HNF4G in lung cancer." (PMID 29719587, 2018). "Collectively, our study suggests that HNF4G is up-regulated in human lung cancer specimens and may be a prognostic marker for lung cancer." (PMID 29719587, 2018).
lung carcinoma (continued). "To investigate the biological functions of HNF4G in lung cancer, we transfected small interference RNAs (siRNAs) targeting HNF4G (siRNA-1, siRNA-2 and siRNA-3) or control siRNA (siNC) into H358 and H292 cells, which expressed relatively higher level of HNF4G." (PMID 29719587, 2018). "First, we studied the expression of HNF4G in lung cancer tissues." (PMID 29719587, 2018). "On the contrary, HNF4G overexpression stimulated lung cancer cell proliferation." (PMID 29719587, 2018). "Thus, we supposed that HNF4G may be involved in the progression of lung cancer." (PMID 29719587, 2018).
gout (5 papers, 2015 to 2022). A condition characterized by painful swelling of the joints, which is caused by deposition of urate crystals. "GWAS have shown TT genotype of rs2941484 of HNF4G to be associated with elevated serum urate, hyperuricemia and/or gout." (PMID 36235682, 2022). "Six of the genes (A1CF, GCKR, ABCG2, TRIM46, SLC17A1 and HNF4G (novel gout-associated gene)) were still significantly associated with gout in males after multiple correction (all PFDR < 0.05)." (PMID 28252667, 2017). "In conclusion, this study systematically revealed the genetic effects on the pathogenesis of gout from elevated serum urate and identified two novel gout-associated genes (HNF4G and SLC17A4)." (PMID 28252667, 2017). "Many researchers have discovered the association of HNF4G with obesity, since rising levels of obesity can contribute greatly to increasing prevalence of hyperuricemia and gout." (PMID 28460474, 2017). "In this study, we systematically analyzed the genetic variants influencing the progression from elevated serum urate to gout and identified 2 novel gout-associated genes (HNF4G and SLC17A4), using genetic analysis and mRNA expression analysis." (PMID 28252667, 2017). "In addition, two novel gout-associated genes, HNF4G and SLC17A4, were found to affect the risk of gout in our study." (PMID 28252667, 2017). "Also, HNF4G is a novel gene associated with susceptibility to gout (OR = 1.28, PFDR = 1.08E-03)." (PMID 28252667, 2017). "Furthermore, two novel gout-associated genes (HNF4G and SLC17A4) were identified." (PMID 28252667, 2017). "Another Chinese study showed that rs10821905 of A1CF gene, rs2941484 of HNF4G gene, and rs4971101 and rs2070803 of TRIM46 gene were associated with susceptibility to gout." (PMID 30123371, 2018). "Our study shows that HNF4G gene expression to be lower in gout patients than in healthy individuals, most likely explaining the mechanism of its effect on the pathogenesis of gout." (PMID 28252667, 2017). "As expected, most of the urate loci are also risk factors for gout, with only four loci (INHBB, HNF4G, UBE2Q2, and BCAS3) yet to be formally associated with gout at a nominal level of significance." (PMID 25889045, 2015). "In addition, to avoid the heterogeneity of gender, logistic regression adjusted for gender was performed to confirm the association for HNF4G and SLC17A4, and the results also showed that those genes influence the risk of gout (PFDR = 8.92E-05 and 0.040, respectively)." (PMID 28252667, 2017). "In this study, HNF4G, SLC17A1 and GCKR played an important role in serum urate concentrations and gout risk in males but not in females, also suggesting the different contributions of genetic effects between different genders." (PMID 28252667, 2017). "Interestingly, three genes (PDZK1, GCKR and HNF4G) associated with urate influenced the risk of gout, but the other five genes (TCF7L2, LRRC16A, ESR1, NRXN2 and ALPK1) did not, suggesting that elevated serum urate concentration is necessary but not sufficient for the pathogenesis of gout." (PMID 28252667, 2017).
colorectal cancer (4 papers, 2018 to 2025). A primary or metastatic malignant neoplasm that affects the colon or rectum. "HNF4G is overexpressed in colorectal cancer (CRC) and promotes CRC cell proliferation via the PI3K/AKT pathway by targeting G protein subunit gamma 12 (GNG12) and protein tyrosine kinase 2 (PTK2)." (PMID 35240026, 2022). "To investigate the relevance of our findings for human biology and disease, we analyzed cancer stem cell (CSC) transcriptomes from patient‐derived and CRISPR‐engineered colorectal cancer organoids for evidence of regulation by Hnf4g." (PMID 29945941, 2018).
hepatocellular carcinoma (4 papers, 2017 to 2021). A malignant tumor that arises from hepatocytes. "This SNP is located is an intronic region of HNF4G gene, at chromosome 8q21.11, which encodes hepatocyte nuclear factor 4 gamma, a transcription factor of the nuclear receptor superfamily whose expression level was increased in five of six clinical human hepatocellular carcinoma samples." (PMID 33879152, 2021). "Interestingly, HNF4G implies a negative regulation by interacting with FOXA1, RXRA, and HNF4A in the human hepatoma cell line and some studies have showed that interrelationships among FOXA1, FOXA2, HNF4A, and HNF4G affect transcriptional regulation." (PMID 29033978, 2017).
diabetes (3 papers, 2018 to 2024). "Among the highly probable genes involved in the pathogenesis of diabetes in GK rat, it has been demonstrated that the overexpression or inhibition of Fam3b, Ptprn2, Ide, Hnf4g, Bad and Bmp4 is associated with the glucose tolerance in rodents." (PMID 30687391, 2018). "HNF4G and PDX1 may induce PDAC-associated diabetes, whereas ABO may induce the causative effect of VTE on PDAC." (PMID 39002386, 2024).
hyperuricemia (3 papers, 2017 to 2022). An abnormally high level of uric acid. "The results of our study was consistent with the GWAS on serum urate concentrations, we found that the TT genotype of rs2941484 in HNF4G gene was associated with hyperuricemia only in Chinese male population." (PMID 28460474, 2017). "In conclusion, this is first time that association between the human HNF4G gene and hyperuricemia has been examined in the Chinese Han population." (PMID 28460474, 2017). "The limitation of this study is based on its cross-sectional sample population, it can't reflect the causal relationship between the HNF4G gene and hyperuricemia." (PMID 28460474, 2017). "Variants in HNF4G are associated with several traits, including the development of hyperuricemia." (PMID 35606693, 2022). "We hypothesized that the association of HNF4G with hyperuricemia may be established via its association with obesity." (PMID 28460474, 2017). "Therefore, the objective of this study was to assess the genetic associations of HNF4G polymorphisms and hyperuricemia in Chinese Han population in Xinjiang." (PMID 28460474, 2017). "Since the plasma free fatty acid may be the reasons leading to obesity and insulin resistance, HNF4G may be associated with hyperuricemia from its association with fatty acids levels." (PMID 28460474, 2017). "The mechanism by which HNF4G may be associated with hyperuricemia is still unclear." (PMID 28460474, 2017). "The aim of the study is to investigate the association between the human hepatocyte nuclear factor 4 gamma (HNF4G) gene and hyperuricemia in Chinese Han population." (PMID 28460474, 2017). "The present data indicates that TT genotype of rs2941484 in the human HNF4G gene might be a gender-specific genetic marker for hyperuricemia in Chinese Han men." (PMID 28460474, 2017).